MFSD6L (major facilitator superfamily domain containing 6 like)
Synonyms: SLC73A2; FLJ35773
Tractability: Antibody: UniProt predicts a signal peptide or a membrane-spanning region.
Gene: Protein-coding gene on chromosome 17 (8,797,110 to 8,799,365, reverse strand). Ensembl gene ENSG00000185156.
Subcellular location: Membrane
Gene Ontology:
Cellular component: membrane
Genetic constraint (gnomAD): Loss-of-function variants: 11 observed, 8.34 expected, observed/expected ratio (o/e) 1.32, 90% interval 0.81 to 1.88. That is too few expected variants to judge how well the gene tolerates losing a copy. Missense variants: 747 observed, 762.09 expected, observed/expected ratio (o/e) 0.98, 90% interval 0.92 to 1.04. Synonymous variants: 336 observed, 339.82 expected, observed/expected ratio (o/e) 0.99, 90% interval 0.9 to 1.08.
Homologues: Orthologues: chimpanzee MFSD6L (98% identical), macaque MFSD6L (92% identical), dog MFSD6L (71% identical), rabbit MFSD6L (69% identical), mouse Mfsd6l (68% identical), guinea pig MFSD6L (67% identical), rat Mfsd6l (61% identical), tropical clawed frog mfsd6l (42% identical), zebrafish mfsd6l (33% identical), Drosophila melanogaster SP1173 (13% identical). Paralogues in human: MFSD6 (20% identical).